CCL20 (C-C motif chemokine ligand 20)
Diseases named in the same sentence as CCL20 in open-access papers (continued):
Sharing a sentence is not in itself a finding about the gene and the disease.
medulloblastoma (1 paper, 2015). A malignant, invasive embryonal neoplasm arising from the cerebellum. "We speculated that IL-17 might promote IFN-gamma, IL-6, IL-23, CCL-20, and Ccl2 expressions in the subcutaneous medulloblastoma model." (PMID 26684834, 2015). "Furthermore, our study showed that injecting IL-17 significantly increased the IFN-gamma, IL-6, IL-23, Ccl2, and Ccl20 chemokine productions in medulloblastoma xenografts in vivo." (PMID 26684834, 2015). "The results also suggest that IL-17 in mice might activate splenocytes and/or medulloblastoma cells to produce chemokines Ccl20 and Ccl2, which might promote splenocyte recruitment and anti-tumor activity." (PMID 26684834, 2015).
meningococcal infection (1 paper, 2025). Infections with bacteria of the species neisseria meningitidis. "Upon meningococcal infection, we observed a mostly universal induction of CCL20, CXCL1, CXCL8, CXCL10, and IL-18 secretion 24 h post-infection, regardless of the specific meningococcal strain used for infection." (PMID 40586572, 2025). "Despite strain and donor variability, meningococcal infection universally induced cytokines CCL20, CXCL1, CXCL8, CXCL10, and IL-18, with significantly higher CCL20 levels 24 h post-MenW cc11 infection." (PMID 40586572, 2025).
mood disorder (1 paper, 2021). A cognitive disorder a disturbance in which the person's mood is hypothesized to be the main underlying feature. "However, to our knowledge an increase of circulating CCL20 has not been reported in patients with mood disorders." (PMID 34584171, 2021).
nasal polyps (1 paper, 2009). "IL-17A and TNF-α synergistically induced MIP-3α/CCL20 production by nasal polyp fibroblasts in a dose- and time-dependent manner." (PMID 23283206, 2009). "The objective of this study was to demonstrate the expression of MIP-3α/CCL20 in nasal polyp fibroblasts after stimulation with proinflammatory cytokines such as interleukin-17 (IL-17) and tumor necrosis factor-α (TNF-α)." (PMID 23283206, 2009). "The release of MIP-3α/CCL20 by the nasal polyp fibroblasts occurred in a dose- and time-dependent manner." (PMID 23283206, 2009). "Our results suggest that IL-17A and IL-17F, but not IL-17E, contribute to infiltration of Th17 cells and DCs into upper airway inflammatory sites such as nasal polyps through the production of MIP-3α/CCL20 by fibroblasts." (PMID 23283206, 2009). "Combined stimulation with IL-17A and TNF-α induced further upregulation of MIP-3α/CCL20 expression in the nasal polyp fibroblasts." (PMID 23283206, 2009). "However, in the present study, we have demonstrated that IL-17A and TNF-α synergistically induced MIP-3α/CCL20 in nasal polyp fibroblasts." (PMID 23283206, 2009). "Although epithelial cells are thought to be the primary source of MIP-3α/CCL20, this study showed that nasal polyp fibroblasts are another source of this chemokine." (PMID 23283206, 2009). "This MIP-3α/CCL20/CCR6 positive-feedback loop involving Th17 cells, DCs, and fibroblasts amplifies the IL-17 inflammatory response in nasal polyps." (PMID 23283206, 2009). "It is interesting to speculate whether IL-17A, which is released from Th17 cells, is capable of inducing MIP-3α/CCL20 production in nasal polyp fibroblasts synergistically with TNF-α, which is abundant in nasal polyps." (PMID 23283206, 2009). "Combined stimulation with TNF-α plus IL-17A or IL-17F, but not IL-17E, synergistically induced release of MIP-3α/CCL20 by the nasal polyp fibroblasts." (PMID 23283206, 2009). "Nasal polyp fibroblasts, by producing MIP-3α/CCL20, may play an important role in the recruitment of T cells and DCs in upper airway inflammatory lesions such as nasal polyps." (PMID 23283206, 2009).
Neonatal sepsis (1 paper, 2025). Systemic inflammatory response to infection in newborn babies. "Other chemokines, including MMP- 10, CCL20, and CXCL1, have also been studied in diagnosing NEC and differentiating it from neonatal sepsis." (PMID 40295408, 2025).
optic neuritis (1 paper, 2024). Optic neuritis is inflammation of the optic nerve, the nerve that carries the visual signal from the eye to the brain.The conditionmay cause sudden, reduced vision in the affected eye(s). "Furthermore, concentrations of CXCL8, CXCL10 and CCL20 in sera did not significantly differ among subgroups of MS patients divided by presence or localization of demyelinating lesions (supratentorial, infratentorial and cervical), sex, or history of optic neuritis." (PMID 39125633, 2024).
osteomyelitis (1 paper, 2025). An acute or chronic inflammation of the bone and its structures due to infection with pyogenic bacteria. "Overall, our study highlights the crucial immunomodulatory role that the CCL20/CCR6 axis plays during osteomyelitis." (PMID 40853122, 2025). "Implant-associated osteomyelitis in C57BL/6, CCL20-/-, and CCR6-/- mice revealed an early increase in planktonic bacterial growth on day 1 and increased bacterial loads in soft tissue and bone on day 14 post-infection in both CCL20-/- and CCR6-/- mice." (PMID 40853122, 2025). "Importantly, in a clinical pilot study, we observed that CCL20 can be a useful biomarker of osteomyelitis-induced septic death." (PMID 40853122, 2025). "However, the role of the CCL20/CCR6 axis in host defense against Staphylococcus aureus osteomyelitis remains unknown." (PMID 40853122, 2025).
osteoporosis (1 paper, 2015). A condition of reduced bone mass, with decreased cortical thickness and a decrease in the number and size of the trabeculae of cancellous bone (but normal chemical composition), resulting in increased fracture incidence. "Based on these findings, we speculate that CXCL8 and CCL20 may play a role in generalized osteoporosis during systemic inflammation in which serum levels of CXCL8 and CCL20 are elevated." (PMID 26103626, 2015). "Based on our findings, we created a pathophysiological model illustrating how CXCL8 and CCL20 might influence bone remodeling in inflammatory conditions and contribute to osteoporosis." (PMID 26103626, 2015).
pancreatic disease (1 paper, 2010). "Likewise, we observed an entirely inconspicuous CCL20 expression profile in PA, a pancreatic disease also suspected to precede the development of PCA." (PMID 20459729, 2010).
papilloma (1 paper, 2020). A benign epithelial neoplasm that projects above the surrounding epithelial surface and consists of villous or arborescent outgrowths of fibrovascular stroma. "We then asked whether expression of CCL1 and CCL20 mRNA by purified monocyte-derived iLCs from controls and patients differed from iLCs isolated from papilloma tissues." (PMID 32210959, 2020). "Immature LCs from the papillomas and foreskin expressed high levels of CCL20 mRNA that were close to GAPDH levels at baseline, with no significant change after removal from their microenvironments or following stimulation with either poly(I:C) or TNFα." (PMID 32210959, 2020). "Unlike CCL1, papilloma-derived iLCs expressed very high levels of CCL20 mRNA at baseline that did not further increase following IL-36γ stimulation (410 ± 65 and 422 ± 80, respectively)." (PMID 32210959, 2020).
pemphigus (1 paper, 2022). Pemphigus is a group of rare autoimmune diseases that cause blistering of the skin and mucous membranes (mouth, nose, throat, eyes, and genitals).This conditioncan occur at any age, but often strikes people in middle or older age. "CCL5 and CCL20 were found to be highly expressed in pemphigus lesions." (PMID 35449056, 2022).
pneumococcal pneumonia (1 paper, 2023). A febrile disease caused by STREPTOCOCCUS PNEUMONIAE. "Moreover, during mouse pneumococcal pneumonia, combined treatment with flagellin and antibiotics augmented the release of Cxcl1 and Ccl20 in bronchoalveolar lavage fluid, the influx of neutrophils, and host defense, as reflected by a reduced bacterial burden in the lung." (PMID 38203480, 2023).
preeclampsia (1 paper, 2025). Preeclampsia is a hypertensive disorder of pregnancy that is characterized by new-onset hypertension with proteinuria presenting after 20 weeks of gestation, and depending on mild or severe forms may initially present with severe headache, visual disturbances, and hyperreflexia. "Furthermore, CCL-20 cord blood levels were associated with preeclampsia and fetal leptin, insulin, IL-8, and IL-10 levels, suggesting its role in pregnancy complications, fetal adiposity, and inflammation." (PMID 40698658, 2025).
prostatitis (1 paper, 2024). An infectious or non-infectious inflammatory process affecting the prostate gland. "CCL20 holds promise as a potential target for prostatitis treatment and a novel diagnostic marker." (PMID 38801403, 2024). "This study illuminated that CCL20 played a pivotal role in attracting Th17 cells to the prostate, thereby contributing to prostatitis development." (PMID 38801403, 2024). "This research highlights the importance of CCL20 as a key mediator in prostatitis pathogenesis, contributing to inflammatory cell infiltration." (PMID 38801403, 2024). "Nevertheless, extensive clinical studies are essential to validate the clinical utility of CCL20 in prostatitis management." (PMID 38801403, 2024).
Pruritus (1 paper, 2023). Pruritus is an itch or a sensation that makes a person want to scratch. "It was shown that the expression of genes encoding inflammatory mediators such as CCL4, CCL7, CCL8, CCL20, interleukin-19 (IL-19), IL-20, IL-26, IL-36A, IL-36G, and TNF-α) was unique to psoriatic skin with pruritus." (PMID 37834183, 2023).
psychosis (1 paper, 2022). "Overall, we found that four factors (CD30, BAFF, CCL20, and CXCL10) might be associated with treatment of psychosis." (PMID 35618730, 2022). "In all the psychosis patients combined, CD30, BAFF, CCL20, CXCL10, and IFN-γ R1 achieved enough power (>80%)." (PMID 35618730, 2022).
psychosomatic disorders (1 paper, 2022). "A previous study showed that GFAP-A patients had significantly higher levels of CSF CCL20 than other patients (MS, NMOSD, and psychosomatic disorders), except patients with varicella zoster virus meningitis." (PMID 35983033, 2022).
pulpitis (1 paper, 2016). Inflammation of the dental pulp. "These previous findings suggest that chemokines, such as IL-8, MCP-1, and CCL20, might play an important role in the progression of pulpitis via recruitment of inflammatory cells into the dental pulp." (PMID 27747243, 2016).
radiodermatitis (1 paper, 2022). A cutaneous inflammatory reaction occurring as a result of exposure to biologically effective levels of ionizing radiation. "Nevertheless, despite reductions in cytokine signaling and radiodermatitis in CCR6−/− mice, Ccl20 mRNA upregulation remained elevated in comparison to naive WT controls, indicating the persistence of pro‐inflammatory signals in these mice." (PMID 35785521, 2022).
rectal cancer (1 paper, 2021). A primary or metastatic malignant neoplasm that affects the rectum. "Several Th17-type proteins including CCL20, IL-17A and IL-17A/F are secreted at higher levels from rectal cancer tissue compared to normal rectal tissue." (PMID 33540635, 2021).
relapsing-remitting MS (1 paper, 2024). "In our study we hypothesized that serum concentrations of CCL20, CXCL8 and CXCL0 are induced in patients with relapsing-remitting MS (RRMS) in comparison to healthy individuals, and that they are associated with EBV infection." (PMID 39125633, 2024).
respiratory infections (1 paper, 2024). "Here, we observed that respiratory infections in nursing infants also induced higher CCL20 concentrations in breast milk, leading to an increase in all CCR6+ T- and B-cell subpopulations." (PMID 39867906, 2024).
sarcoma (1 paper, 2018). A usually aggressive malignant neoplasm of the soft tissue or bone. "The negative correlations between the expression of IL-33 and CCL20 and TGFB1 were then validated by analysis using GSE6481 or GSE967 datasets of sarcoma." (PMID 29896199, 2018).
SARS-CoV infection (1 paper, 2014). "The receptor for CCL20, CCR6 was significantly down regulated with age and SARS-CoV infection on peripheral blood DCs (2-way ANOVA for age and d.p.i.)." (PMID 24642138, 2014).
simian immunodeficiency virus infection (1 paper, 2018). An infection affecting monkeys, chimpanzees, and other non human primates caused by a HIV-like virus. "In fact, chemokines such as CCL20 have been used as adjuvants for several cancer vaccines and for DNA vaccines against simian immunodeficiency virus infection." (PMID 29434590, 2018).
skin changes (1 paper, 2020). "In line, no alterations in measured serum chemokine levels (IL-17A/F, IL-23, IL-18, CCL20, and CCL27) were observed either, confirming a weak relationship between serum cytokines and skin changes in all but most severely affected individuals." (PMID 33343564, 2020).
syphilis (1 paper, 2016). A contagious bacterial infection caused by the spirochete Treponema pallidum. "We found that patients affected by tertiary syphilis possess TpF1-specific T cells and that these cells, once activated by TpF1, but not by the control antigen (tetanus toxoid, data not shown), stimulate HUVECs to secrete IL-8 and CCL-20." (PMID 26728351, 2016).
thymoma (1 paper, 2021). A neoplasm arising from the epithelial cells of the thymus. "CCL20, a member of CC family and the alpha subfamily chemokines, was found down-expressed in thymoma associated MG in our exploration." (PMID 34777476, 2021). "According to previous study, an increase of T lymphocytes may have a link to thymoma-related MG, while the capacity to activate T lymphocytes were different in dendritic cells that induced by different level of CCL20." (PMID 34777476, 2021).
thyroiditis (1 paper, 2020). Inflammation of the thyroid gland. "A study conducted in a large series of PTCs with and without associated thyroiditis showed that CCL20 and CXCL8 were significantly higher in PTC samples compared to normal thyroid, regardless of the tumor genetic background and the presence or absence of thyroiditis." (PMID 33986723, 2020).
tongue cancer (1 paper, 2021). A malignant neoplasm affecting the tongue. "Tongue cancer cell-derived CCL20 that was induced by interaction with macrophages promotes CD163 expression on macrophages." (PMID 34178651, 2021).
tuberculous pleurisy (1 paper, 2022). "It has been reported that CCL20 expression by pleural mesothelial cells could partly facilitate the recruitment and differentiation of helper T cells in tuberculous pleurisy." (PMID 35841069, 2022).
ulcer (1 paper, 2023). "In contrast, the expression levels of the immune-related gene Ccl20 were increased in the HMLS group, suggesting a potential amelioration of indomethacin-induced ulcer symptoms." (PMID 38139257, 2023).
urothelial carcinoma (1 paper, 2022). A malignant neoplasm derived from the transitional epithelium of the urinary tract (urinary bladder, ureter, urethra, or renal pelvis). "Using another independent cohort of 348 urothelial carcinoma patients treated with the anti-PD-L1 agent (atezolizumab), we explored the synergistic effect of CCL20 and TGF-β on immunotherapy efficacy." (PMID 35864953, 2022).
uveitis (1 paper, 2022). An inflammatory process affecting a part of or the entire uvea. "Notably, our previous induced uveitis rodent studies demonstrated SOCS1-KIR mediated decreases in the chemokines CCL2, CCL20 and CXCL9, in addition to the chemokine receptors CCR2, CCR4, CCR6 and CXCR35,25." (PMID 35505065, 2022).
vaginal candidiasis (1 paper, 2011). "The lack of CCL20 production by vaginal ECs is likely to reduce the rate of myeloid/lymphoid cell infiltration into vaginal tissues during C. albicans infection, resulting in poor activation of cellular immunity that is a typical feature of vaginal candidiasis." (PMID 22087232, 2011).
viral myocarditis (1 paper, 2017). Myocarditis that is caused by an infection with a viral agent. "Furthermore, the administration of a CCL20-neutralising antibody improved the prognosis in CVB3-induced acute viral myocarditis by decreasing CCR6+ Th17 cell recruitment." (PMID 28798316, 2017).
vitamin D (1 paper, 2013). "Increased expression of CCL19 mRNA was observed in the CD11c+ cells from male vitamin D-deficient mice, when compared to their vitamin D-replete counterparts, while vitamin D deficiency down-regulated the expression of mRNAs of CCL11, CCL19, CCL20 and CXCL1 in CD11c+ cells from female mice." (PMID 23826346, 2013).